IL6 (interleukin 6)
Diseases named in the same sentence as IL6 in open-access papers (continued):
Sharing a sentence is not in itself a finding about the gene and the disease.
tumor (continued). "According to analysis of clinical samples and experimental studies, we found that the accumulated CD4+ cells in the stroma are the main source of IL-6, which in turn triggers the tumor cell EMT that induces the mesenchymal phenotype of tumor cells." (PMID 28846080, 2017). "IL-6 also down regulate clinical outcome by maintaining abundant therapeutic resistant cancer stem cells which is play crucial role in tumor reoccurrence and resistance." (PMID 29296206, 2017). "IL-6 is known to alter the phenotypes of various cell types within the tumor microenvironment to secrete chemokines and VEGF, enhance vasculature permeability and angiogenesis, and promote tumor cell dissemination and metastasis." (PMID 28416734, 2017). "The cytokine interleukin-6 (IL-6) has pleiotropic effects on various cell types in the tumor microenvironment and is a regulator of the pro-oncogenic transcription factors NF-κB and STAT38." (PMID 28851899, 2017). "IL6 is one of the major pro-inflammatory cytokines in the tumor microenvironment, and promotes cancer progression and therapeutic resistance." (PMID 29048388, 2017). "Other studies also indicate that bortezomib inhibits the pro-tumor effects of IL-6, TGFβ, VEGF etc. and decreases tumor angiogenesis." (PMID 28052005, 2017). "Additional tumor-mediated mechanisms are responsible for stimulating osteoclasts in human MM, including IL-1, IL-6, tumor necrosis factor-α (TNF-α), TNF-β (lymphotoxin), RANKL, MIP-1α and PTHrP, among others." (PMID 29056680, 2017). "In particular, tumor-derived interleukin-6 (IL-6) led to an increase in the number of activated platelets." (PMID 28894697, 2017). "The cytokine interleukin-6 (IL-6) has pleiotropic effects on various cell types in the tumor microenvironment." (PMID 28851899, 2017). "IL6 was reported to stimulate STAT3 activity which promotes tumor growth and survival of NSCLC via JAK/STAT3 signalling." (PMID 28427199, 2017). "Strong membrane E-cadherin expression was observed in tumors from Losartan-treated mice compared to control mice (P < 0.05), suggesting a potential IL-6-mediated inhibition of tumor de-differentiation following ARB treatment." (PMID 28416734, 2017). "We then used both tumor cells and macrophage cells, two of the many different sources of IL-6, to detect the effect of SH on IL-6 production in vitro." (PMID 28088791, 2017). "We also found a decrease in IL-6 secretion levels that strongly correlated with tumor growth inhibition." (PMID 27577074, 2017). "In fact, PF in OC patients creates a complex and highly pro-tumor microenvironment with elevated levels of IL-6, IL-8, IL-10, IL-15, IP-10, MCP-1, MIP-1β, and VEGF." (PMID 28589429, 2017). "SDF1A was expressed in CAFs while CXCR4 was active in PDAC cells, where IL-6 was also induced, again demonstrating the close interplay between stromal and tumor cells." (PMID 28351381, 2017). "When endogenous IL-6 is silenced, cell cultures derived from positive SA-β-gal human tumor samples decrease the expression of the senescence marker." (PMID 27902467, 2017). "In myeloid cells, activation of NF-κB increases the secretion of proinflammatory cytokines, such as TNF-α and IL-6, which enhance the inflammation and eventually leads to a rapid proliferation of tumor cells." (PMID 28402257, 2017). "Tissue-resident fibroblasts are suggested as precursors for CAFs, activated by tumor and immune cell-derived factors to express pro-inflammatory genes such as IL-1, IL-6, IL-8 and SDF-1." (PMID 28186964, 2017). "Cancer-associated stroma secretes a plethora of factors such as HGF, IL-6, TGF-β to promote the growth and invasion of the underlying tumor." (PMID 28186964, 2017). "Various pro-inflammatory cytokines such as tumor necrosis factor-α, interleukin-1, and interleukin-6 are upregulated concomitantly with tumor progression." (PMID 29216259, 2017).
tumor (continued). "α-SMA (+) CAFs, CD68 (+) tumor stromal TAMs, and IL-6 (+) tumor stromal cells were significantly higher in moderately/poorly differentiated HCCs, compared to well differentiated HCCs (P <0.05 for all)." (PMID 28114366, 2017). "In this study, inhibition of IL-1 and IL-6 genes in inflammatory cells suggests that blocking can also happen in tumor cells, which produce these cytokines, favoring the tumor progression." (PMID 28785138, 2017). "Cancer cells produce various cytokines, such as tumor necrosis factor-α and interleukin-6, and this phenomena can increase the number of tumor-infiltrating neutrophils around a tumor." (PMID 28039452, 2017). "In this study, we found that tumor-derived IL-6 triggers the differentiation and immunosuppressive activity of MDSCs." (PMID 29326716, 2017). "Here, we observed that IL-6 knockout endothelial cells resulted in slow tumor growth with smaller fraction of cancer stem cells." (PMID 29245982, 2017). "Siltuximab is a chimeric anti-IL-6 antibody, and it was studied for its advantageous anti-IL-6 effects on tumours, such as MM." (PMID 29089667, 2017). "Further investigation into the mechanisms via which AT1R and IL-6 drive tumour epithelial cell de-differentiation and effects on immune cells including the cytotoxic T cell function and macrophage-polarisation status are warranted." (PMID 28416734, 2017). "Our findings on IL-6, a pro-survival cytokine that can transform cells to a “pro-inflammatory cell”, also indicate a potential approach for inhibiting IL-6 secretion, tumor progression and chemotherapy resistance development." (PMID 28420874, 2017). "IL-6-enhanced tumor sphere-forming ability was disrupted significantly as the size and the number of formed spheres was significantly less comparing to IL-6-induced counterparts." (PMID 28241877, 2017). "IL-6 is a pleiotropic cytokine, which is produced mainly by lymphocytes, macrophages, epithelial cells, tumor cells, and also FLS in humans." (PMID 28659662, 2017). "Interleukin-1 (IL-1) and interleukin-6 (IL-6) are expressed by senescent epithelial cells, fibroblasts, and other cell types and can induce either cellular senescence or tumor formation in neighboring cells." (PMID 29218300, 2017). "Among the chronic inflammation associated mediators, tumor necrosis factor alpha (TNFα), interleukin-6 (IL-6), vascular epidermal growth factor (VEGF), and MMPs are of particular attention for their role in tumor development." (PMID 28076322, 2017). "Plasma inflammatory cytokines were significantly elevated in the tumor bearing group; TNF-α was over two-fold and IL-6 was over eight-fold higher in tumor-bearing mice compared to Sham animals." (PMID 29033844, 2017). "Elevated IL-6 levels in patients with HNSCC correlate with higher tumor stage, lymph node metastasis, increased proliferative tumor-activity, decreased immunologic response, and distinctive cachexia." (PMID 28872582, 2017). "Numerous studies show that IL-6/STAT3 signaling pathway plays an important role in tumor metastasis." (PMID 29100297, 2017). "The release of IL-6 is biologically related to an induction of tumor cell proliferation and inhibition of cellular apoptosis through the involvement of Janus kinases (JAKs) and signal transducer and activator of transcription 3 (STAT3)." (PMID 28264501, 2017). "Dedifferentiation markers, CK20 and CDX1, and inflammatory cytokine IL6 were also elevated in these tumours as was the EMT transcription factor Snail." (PMID 28300841, 2017). "Herein, we provide an overview of the current understanding of the role of the best-validated cytokines involved in tumor progression, IL-1, IL-4 and IL-6; in addition to IL-2 cytokines family, which is known to promote tumor eradication by immune cells." (PMID 28927416, 2017). "IL-6 secreted from either cancer cells or tumor microenvironment (immune cells and tumor stromal cells) not only facilitates tumor growth but also acts as a major barrier in achieving therapeutic efficacy." (PMID 29296206, 2017).
tumor (continued). "For instance, MM cells can educate MSCs to acquire a tumor-like phenotype with the ability to secrete interleukin-6 (IL-6), IL-8, and TNF-β, which further promote MM survival." (PMID 29333170, 2017). "The epigenetic regulation of gene expression by IL-6 can lead to tumor progression by altering the promoter methylation and the genes regulatory pathways." (PMID 28101335, 2017). "Recently, tumor-derived factors released into circulation were shown to induce mitophagy in skeletal muscle through IL-6-dependent signaling." (PMID 28785374, 2017). "Recently, we have shown that IL-6 promotes tumor metastasis by inducing epithelial-mesenchymal transition (EMT)." (PMID 28978005, 2017). "Our data suggest that MEPs prevent the tumor-promoting actions of CAFs by blocking secretion of proinflammatory factors, including IL-6, into the tumor microenvironment." (PMID 28506312, 2017). "Excess body weight is considered a chronic inflammatory state characterised by increased adipose secretion of proinflammatory cytokines, such as interleukin-6 (IL-6), which has been shown to promote tumour initiation in experimental models." (PMID 29259258, 2017). "Recently, experiments performed with orthotopic mouse models of ovarian cancer demonstrated that tumor cell-derived IL-6 stimulates hepatic production of TPO." (PMID 28681240, 2017). "The tumor promoting arm of that balance is determined by the presence of cells of myeloid origin, Type 2 suppressive T-cells (Tregs) and Th2-cells and IL-4, IL-6, IL-10 and IL-13 are relevant cytokines." (PMID 28402937, 2017). "In the present study, we aimed to investigate alterations of the tumor stroma in SH-HCCs, comparing the expression of CAFs, HSCs, senescence-associated proteins, and SASP factors (p21Waf1/Cif1, γ-H2AX, and IL-6) between SH-HCCs and C-HCCs." (PMID 28273155, 2017). "IL-6 is an important inflammatory mediator and the effects of IL-6 on angiogenesis during tumor progression have been demonstrated." (PMID 28467355, 2017). "iTAMs are further hallmarked by the expression of CD86high, CD206low, Cd163high, Hmox1high, show a pro-inflammatory phenotype associated with the production of ROS and pro-inflammatory cytokines (TNFα and IL-6), and are capable of killing tumor cells." (PMID 29167669, 2017). "Nuclear pSTAT3, which localised to tumor epithelial cells and stroma in control mice, showed reduced expression in Losartan-treated tumors, reflective of the decrease in IL-6 levels." (PMID 28416734, 2017). "One hallmark feature of senescence is that senescent cells express and secrete cytokines and growth factors to increase the complexity of tumor microenvironment, which is termed senescence-associated secretory phenotype (SASP), including IL-6, IL-828." (PMID 28646235, 2017). "Collectively, it is suggested that IL-6 is a critical tumor promoter in colitis-associated cancer and STAT3 is essential for the transduction of tumor-promoting signals from IL-6." (PMID 28852270, 2017). "IL-6 has a bifunctional role in tumor microenvironments by exerting a protumor response with respect to tumor angiogenesis and an anti-tumor T cell response with respect to tumor growth." (PMID 28905322, 2017). "Others have also demonstrated a tumor-promoting role in breast and ovarian cancers for IL-6 secreted from CAFs." (PMID 28506312, 2017). "Proinflammatory cytokines such as IL-6 and IL-1 are believed to be indispensable for cancer progression, and anti-inflammatory drugs have been proposed to treat tumours." (PMID 29089667, 2017). "This further substantiates the key role of paracrine IL-6 in cervical carcinogenesis for the initiation and maintenance of chronic inflammation and tumor progression." (PMID 28895886, 2017). "In multivariate analysis, tumor grade and IL-6 level remained significant prognostic factors of survival (p = 0.02 and p = 0.02, respectively)." (PMID 28851899, 2017).
tumor (continued). "The pro-inflammatory cytokines; IL-1β, IL-6, TNF-α and GM-CSF have been implicated in cell biology changes required for tumour progression." (PMID 28427184, 2017). "Elevated IL-6 has been shown to confer cancer cells with chemotherapy resistance and contribute to tumor recurrence and metastasis." (PMID 29088851, 2017). "Among the soluble factors contributing to TAM polarization, tumor progression, and a poor clinical outcome, IL-6, IL-10, TGFβ, and AA play a prominent role." (PMID 28275576, 2017). "Our results suggested that the tumor suppressive effect of GMI was mediated through inhibition of IL-6/Stat3 signaling pathway." (PMID 29050290, 2017). "Interleukin-6 (IL-6) is a multifunctional cytokine, which is involved in the regulation of differentiation and growth of certain types of tumor cells." (PMID 28430601, 2017). "We show that elevated expression of IL-6 alone in the prostate is sufficient to induce local neoplasm." (PMID 28077171, 2017). "Many lines of evidence demonstrate that IL-6 promotes tumor progression in multiple ways, including enhanced angiogenesis and lymphangiogenesis." (PMID 28978186, 2017). "Our results suggest that elevated levels of serum Shh and IL-6 most likely also originate from lymph node metastases, potentially, and overall are likely accountable for the increased tumor burden, and life-threatening progression and metastasis." (PMID 28496132, 2017). "We were unable to detect detrimental levels of IL-12 or IL-6 in tumor-bearing animals treated with armored CAR T cells." (PMID 28874817, 2017). "For instance, IL-6 can contribute to tumor cell survival and upregulate the antiapoptotic genes by driving JAK2/STAT3 signal; IFN-ɤ activates macrophage by JAK-STAT signaling pathway." (PMID 28630636, 2017). "IL-6 trans-signaling results in strong phosphorylated STAT3 expression and a significantly increase tumor-associated antigens carcinoembryonic antigen-related cell adhesion molecule 5/6 (CEACAM5/6) expression." (PMID 28725043, 2017). "Our study adds another potential regulatory mechanism involving microRNA, CPEB1, and IL6 within the complex microRNA-network of tumor microenvironment." (PMID 28333977, 2017). "Increased IL-6 level predicts tumor recurrence, a poor response to chemotherapy, poor survival, and tumor metastasis." (PMID 29147673, 2017). "S1PR1 in tumor cells was previously shown to be linked to STAT3 activation, which contributed to stimulated IL-6 production." (PMID 28771545, 2017). "Our further results showed that the expression of IL-6, a prominent proangiogenic factor involved in angiogenesis during tumor progression, was significantly decreased in Atg7-silenced HBMEC compared to the control." (PMID 28467355, 2017). "IL-6 (+) tumor stromal cells also significantly increased with progression of multistep tumorigenesis (P <0.001)." (PMID 28114366, 2017). "IL-6, a major trigger of the signal transducers and activators of transcription 3 (STAT3) signaling pathway, have been implicated in regulation of tumor growth and metastasis of BCa." (PMID 29190997, 2017). "Using a standard murine DC culture system in vitro, it was found that addition of tumor-derived exosomes induced expression of interleukin-6 (IL-6) and inhibited differentiation of bone marrow precursor cells into DCs." (PMID 28659795, 2017). "It is suggested that suppression of TGF-β signaling promotes tumor growth in an IL-6/STAT3-dependent way." (PMID 28852270, 2017). "TAMs release certain factors, such as TGF-β, interleukin-6 (IL-6), and IL-8, that affect the formation of the tumor microenvironment." (PMID 29245941, 2017). "IL-6 is considered a mediator of monocyte-mediated proliferation of tumor cells through its binding to the IL-6 receptor (IL-6R)." (PMID 29207662, 2017).
tumor (continued). "Meanwhile, IL-6 together with mechanical compression enhances tumor progression of tumor and triggers a subset of cancer cells to complete EMT and gain stemness, while other cells which are hindered from rapid evolution are killed in the process." (PMID 28846080, 2017). "Among the soluble factors contributing to TAM polarization, tumor progression and a poor clinical outcome, interleukin 10 (IL-10), IL-6, transforming growth factor β (TGFβ) and arachidonic acid play a prominent role." (PMID 28327095, 2017). "Plasma levels of tumor-derived human IL6 and CXCL1 were indeed ablated in WCE-treated mice compared to vehicle-treated mice." (PMID 29142311, 2017). "We discovered that the TNBC tumor cells secrete large amounts of interleukin-6 (IL-6) that induced lymphatic endothelial cells (LEC) in the LN and lungs." (PMID 28947965, 2017). "IL-6 is produced by a wide variety of cell types including immune cells (macrophages, dendritic cells and B-cells), endothelial cells and tumor cells." (PMID 28978005, 2017). "Further, tumor-induced elevation of circulating TNFα and interleukin-6 (IL-6) was abolished in TLR4−/− mice." (PMID 28536426, 2017). "The strength of this work lies in the fact that patients were enrolled in this prospective study at the time of diagnosis and all patients were untreated at the time of sample collection implying that serum Shh/IL-6 mirrors tumor progression." (PMID 28496132, 2017). "IL-6 overexpression in tumor-bearing mice can activate AMPK and reduce PGC-1α expression, whereas IL-6 receptor antibody administration attenuates cancer-induced AMPK activation." (PMID 28785374, 2017). "Recent studies have revealed that TAMs release certain factors, such as TGF-β, interleukin-6 (IL-6), and IL-8, that affect the tumor microenvironment." (PMID 29245941, 2017). "We found a positive correlation between baseline IL-8 and IL-6 microdialysis levels in tumor tissue and survival." (PMID 27664151, 2017). "Elevated interleukin-6 (IL-6) has been observed in almost all types of tumors acting as a major pro-inflammatory mediator in tumor microenvironment." (PMID 28615714, 2017). "We have previously reported that the inhibition of IL-6 signaling alone is insufficient to inhibit 786-O tumor growth in vivo." (PMID 28903416, 2017). "Functional effects of genetic knockdown and overexpression of IL6R or IL6 stimulation were examined in vitro and in tumours in vivo." (PMID 29258522, 2017). "MDSC arise from myeloid precursors in response to tumor-derived growth factors and pro-inflammatory cytokines (e.g., IL-6, GM-CSF), and their numbers correlate with tumor burden and are predictive of low overall survival." (PMID 29133913, 2017). "Elevated IL-6 level predicts tumour recurrence, poor response to chemotherapy, poor survival and tumour metastasis." (PMID 28198361, 2017). "In recent studies, the association between tumor progression, metastasis and inflammatory mediators TNF-α, IL-6, vascular endothelial growth factor (VEGF) and C-C motif chemokine receptor 7 (CCR7) have also been investigated." (PMID 29299026, 2017). "IL-17 promotes tumor neovascularization in nude mice via induction of IL-6 and MDSCs indirectly or supporting neoplastic growth directly." (PMID 28002798, 2017). "In human and murine in vitro co-culture studies, we demonstrated that NBL-TAM interactions led to increased IL-6 levels in the media, increased tumor cell proliferation and decreased apoptosis." (PMID 29207662, 2017). "Increased interleukin-6 (IL-6) has been found in almost all types of tumors acting as a major cytokine in the tumour microenvironment." (PMID 28978076, 2017). "Given that we observed a reduction in the levels of proinflammatory cytokines IL-6, IL-1β and TNFα within the tumour, we investigated changes in immune cell populations within the tumour and its microenvironment." (PMID 28416734, 2017).